CD79A (CD79a molecule)
Diseases named in the same sentence as CD79A in open-access papers (continued):
Sharing a sentence is not in itself a finding about the gene and the disease.
tumor (582 papers, 1973 to 2026). "To further demonstrate the importance of humoral immunity, we treated B cell-deficient CD79a knockout mice with neoadjuvant combination therapy followed by the tumor rechallenge 2 weeks later." (PMID 40897896, 2025). "In contrast, in malignant tumours, an inverse association was observed between CD79a expression and the presence of IgG, accompanied by a significant increase in tumour antigen-specific IgG." (PMID 41040928, 2025). "By analyzing the TCGA and GEO database and applying ESTIMATE algorithm and a series of bioinformatic methods, we obtained tumor microenvironment associated genes (CD79A, CXCL13, IL6 and CCL19), which were related to the clinical outcome of PRCC patients." (PMID 33993869, 2021). "High immune infiltration of CD79a+ B cells in the tumor stroma tends to be associated with good survival in colorectal liver metastasis patients." (PMID 33371790, 2021). "Immunohistochemistry showed in two cohorts that high immune infiltration of CD79A+ B cells and K/L+ plasma cells in tumour stroma tended to be associated with good survival." (PMID 32195184, 2020). "Stimulation of BM myeloid cells by crosslinking CD79a induced the secretion of several cytokines associated with tumor and metastasis promotion, in particular IL-6, RANTES, TNFR-II, CXCL16 and CCL22." (PMID 24146823, 2013). "The B cell receptor CD79A is implicated in tumor promotion by myeloid cells." (PMID 37897503, 2023). "In addition, high stromal CD79A+ infiltration was also associated with smaller tumour size [3.4 cm (2.0–4.5) vs. low CD79A+ infiltration 4.1 cm (3.0–7.0); p = 0.011]." (PMID 32195184, 2020). "Changes in phosphorylation to the peptide corresponding to regions of CD79A, the immunoglobulin-associated alpha chain of the B-cell antigen receptor complex, further suggest the importance of studying the impact of tumor microenvironments on immune system function." (PMID 29946469, 2018). "The CD79a+ myeloid cells caused a significantly greater stimulation of tumor growth." (PMID 24146823, 2013). "Several of the top-ranked genes–MS4A1 (CD20), FCRL5 and CD79A–are closely associated with B-cell functions, suggesting that variations in humoral and antigen-presenting activity may critically modulate anti-tumor immunity." (PMID 40745034, 2025). "Immunohistochemistry profiling of the PDX model and cell-line were consistent with the patient’s primary tumour sample (CD3 + /CD30 + /CD79a-)." (PMID 40715645, 2025). "One case showed variable staining of CD20 and CD79a in 90% of tumour cells, and was positive for BCL6 (weak) and MUM1 (strong)." (PMID 41047873, 2025). "We observed expression of tertiary lymphoid structure (TLS)-associated gene signatures including CD79A, CXCL8, and IL7R (interleukin-7 receptor) which supports the presence of well-organized TLS within the tumor microenvironment." (PMID 40950184, 2025). "In this case, the tumor cells expressed CD79a and PAX-5, along with high expression of c-Myc and Bcl-2, which closely resembled the characteristics of “double-expressor DLBCL” in terms of pathological morphology." (PMID 41561755, 2025). "The tumor cells expressed mature B cell-associated antigens CD20 and CD79a, and the vascular endothelial markers CD31 and CD34 showed that the tumor cells were filled in the blood vessels, infiltrated blood vessel walls, and perivascular areas." (PMID 39414604, 2024). "Studies have shown that anti-CD79b immunoconjugates with potent payloads like MMAF or DM-1 induce sustained tumor regression or complete remission in preclinical models, whereas ADCs targeting CD79a often result in tumor relapse." (PMID 39770542, 2024). "Multiple immune-associated genes such as CD79A, CD3E, CD3D, ZAP70, CXCR6, and GZMA were upregulated in hot tumor regions." (PMID 38803565, 2024).
tumor (continued). "B-cells (CD79A) were almost exclusively found in stromal areas (sTILs), T-lymphocytes and macrophages were also present in tumour cell areas (iTILs), while natural killer cells (CD56) were nearly missing in any area." (PMID 36726072, 2023). "CD79a+ B cell infiltration is higher in the epithelial and stromal compartments of high-grade tumours than in those of low-grade tumours from both sexes." (PMID 36928373, 2023). "In summary, we believe that CD79A expression not only affects the infiltration abundance of B lymphocytes in tumor tissues but can also be used as a potential target to analyze and predict the clinical prognosis of patients." (PMID 37344840, 2023). "To detect B lymphocyte infiltration in the spleen, we performed CD79a immunohistochemical staining and found that massive tumor infiltration was observed in the SF3B1WT group compared to SF3B1K700E group." (PMID 37562845, 2023). "In the process of immunotherapy, the tumor microenvironment can be remodeled by targeting elimination of CD79A+CD24-PANCK+-BCSCs subpopulation or reversing the exhaustion of CD8+ T-cell, so as to restore the anti-tumor effect of effector T-cell." (PMID 38066053, 2023). "Since B-cells were predominantly found in stromal regions, the vast majority of tumours were CD79A-excluded (84.5%)." (PMID 36726072, 2023). "CD79A can predict the infiltration abundance of B lymphocytes in the tumor microenvironment of patients with OSCC." (PMID 37344840, 2023). "We then analyzed the cytoplasm of the tumor cells, which was labeled by the intracellular CD79a antibody in a fluorescent double stain." (PMID 35173297, 2022). "Lymph node specimens were immunohistochemically analyzed for CD8+, FoxP3+, and CD79a+ lymphocytes, CD204+ tumor‐associated macrophages (TAMs), and alpha‐smooth muscle actin‐positive cancer‐associated fibroblasts (αSMA+ CAFs)." (PMID 35023268, 2022). "Expression of both CXCL13 and CD79A has been linked to TLS, which in turn is predictive of tumor response to immunotherapy and favorable outcome in many tumor types, including MIBC27–30." (PMID 35027623, 2022). "Four tumor microenvironment-related genes (CD79A, CXCL13, IL6 and CCL19) were identified as biomarkers for PRCC prognosis." (PMID 33993869, 2021). "The C2 cluster of cells were follicular B cells (MS4A1/CD20 and CD79A/B), which were found in lymphoid follicles of tertiary lymphatic structure within the tumor, and C0 and C4 clusters were antibody-secretory cells (MZB1 and SDC1/CD138)." (PMID 34367994, 2021). "We further divided the NSCLC samples into two groups, the naïve-like Bhigh group and the naïve-like Blow group, according to the infiltration level of the CD20+CD79A+ cells in tumor tissues." (PMID 32580738, 2020). "Two genes were found to be independently associated with tumor size (pT4 vs pT1-3): IFITM2 and CD79A." (PMID 33110100, 2020). "The tumor cells were positive for CD45 confirming their hematopoietic origin and positive for CD79a, validating their derivation from the original tumor cell line, which demonstrated CD79a staining in vitro." (PMID 31516393, 2019). "In situ hybridization for miR detection in the paired resected human PDAC tissues showed that miR-125b-5p and miR-99a-5p are highly expressed in inflammatory cells in the tumor stroma, located in clusters of CD79A expressing cells of the B-lymphocyte lineage." (PMID 34484811, 2019). "Immunohistochemistry (IHC) showed positivity for CD138 and EMA in the neoplasm; CD79a in a strong and diffuse pattern through the neoplasm; CD56 in the membrane; and lambda in a focal pattern in the neoplasm." (PMID 27980867, 2016). "On the other hand, MPO positivity is a prominent feature for a tumour of myeloid origin that overrides the unusual and aberrant antigen expression (CD79a, CD99)." (PMID 27019694, 2016). "Immunohistochemically, the tumor cells were strongly positive for CD79a, CD138, CD38 and MUM-1, as well as the presence of kappa light chain restriction." (PMID 26376733, 2015).
tumor (continued). "In EMP portion, the tumor was composed of monomorphic plasmacytoid-appearing cells with immuno-positive to CD79a, CD138, CD38, MUM-1 and CD56, but lack immunoreactivity to pan-CK (AE1/AE3), CD20, CD21 and EBERs." (PMID 26376733, 2015). "Immunohistochemical staining of the tumor cells expressed positivity for CD 20, CD79a, PAX 5, CD 15, and CD 30 consistent with DLBCL and CHL." (PMID 26380128, 2015). "We have provided evidence that CD79a activation by tumor-derived factors contributes importantly to maintaining the immature phenotype in myeloid cells and to enhancing their immune suppressive and pro-tumorigenic activities." (PMID 24146823, 2013). "Staining of the SCP tumor cells for immunomarkers usually reveals positivity for CD79a, CD138 (syndecan-1, plasma cell specific marker), and epithelial membrane antigen (EMA), as well as negativity for pan-B-cell antigens, CD19, and CD20." (PMID 24260722, 2013). "In the present study we unexpectedly found expression of CD79a on immature BM-derived myeloid cells, and on tumor-induced MDSCs in multiple mouse tumor models and in human cancer patients." (PMID 24146823, 2013). "While evaluating CD79a expression in tumor-bearing mice, we also observed a small myeloid cell population that expresses CD79a in the spleen and lungs of naïve mice." (PMID 24146823, 2013). "Most importantly, activation of CD79a on MDSCs enhanced tumorigenesis and metastasis in the mouse models, suggesting a functional role for myeloid CD79a in promoting tumor progression." (PMID 24146823, 2013). "Staining with CD79a(v-20) together with CD79-11 showed that both antibodies recognize B cells from naïve spleens as well as myeloid cells from spleens of tumor bearing mice." (PMID 24146823, 2013). "In the present study, while analyzing the role of B-cells in metastatic cancer progression, we made the unexpected finding that CD79a is expressed on naïve immature BM myeloid cells, and on MDSCs in tumor-bearing animals." (PMID 24146823, 2013). "High CD79A expression may be related to the abundance of tumor-infiltrating B cells, suggesting its essential role in tumor immune surveillance and immune responses." (PMID 40881693, 2025). "IHC demonstrates B-cell marker expression (e.g., CD20, CD79a) in tumor cells." (PMID 41445799, 2025). "In DLBCL, somatic mutations in genes such as CD79A, CD79B, and CARD11 drive ligand-independent persistent activation of BCR signaling, thereby providing sustained proliferative and survival signals that promote tumor progression." (PMID 41142795, 2025). "Immunohistochemistry showed that the tumor cells were CD79a+, PAX-5+, MUM1+, and CD20-." (PMID 36581860, 2022). "Moreover, the strong correlation between CD79A and risk score, B cells, T cells, TIGIT, BTLA, CD27, and TNFRSF17 revealed the crucial role of CD79A in regulating the tumor microenvironment (TME) in LUAD patients." (PMID 35295857, 2022). "In this study, we found that the low-risk group had significantly higher CD79A and CSF3R expression than the high-risk group, which suggests that tumor immunity might be related to somatic mutations." (PMID 33371790, 2021). "Furthermore, CD79A, also known as the B-cell antigen receptor complex, plays a functional role in the tumor-promoting effects of myeloid cells." (PMID 34795689, 2021). "Since the presence of tumor-infiltrating B cells was usually correlated to better overall survival and treatment outcomes, we selected several representative B-cell signatures (CD79A, MS4A1, IGHD, and FCRL4) and examined their prognostic values in NPC patients." (PMID 33750785, 2021). "Immunohistochemical markers that showed to be associated with good survival in the total cohort were: high K/L+ infiltration in tumour stroma [p = 0.029; OR 2.500 (95% CI 1.100–5.682)] and high CD79A+ infiltration in tumour stroma [p = 0.036; OR 2.428 (95%CI 1.062–5.552)]." (PMID 32195184, 2020).
tumor (continued). "We obtained results on the correlation between TPPP3 expression and marker genes of tumor infiltration-associated immune cells, including CD8+T cells (CD8A and CD8B), B cell (CD19 and CD79a), and Myeloid dendritic cell (HLA-DPB1, HLA-DQB1, HLA-DRA, HLA-DPA1, CD1C, NRP1, and ITGAX)." (PMID 33083464, 2020). "Additionally, tissue of resected HCCs was stained for CD20, CD79a and immunoglobulins and analysed for the respective cell numbers separately for tumor, infiltrative margin and distant liver stroma." (PMID 29050338, 2017). "Tumour cells were positive for CD79a, CD20, CD43, CD10, MUM1, and Ki67 (100%)." (PMID 24511310, 2014). "BCL6 and CD79a were expressed in the tumor cells of both components in all cases." (PMID 24885870, 2014). "We propose that CD79a plays a functional role in the tumor promoting effects of myeloid cells, and may represent a novel target for cancer therapy." (PMID 24146823, 2013). "One of the main characteristics of MDSCs is their ability to suppress anti-tumor T cell activity, so we next tested whether crosslinking CD79a has an effect on inhibition of T cell proliferation by BM myeloid cells." (PMID 24146823, 2013). "Here we showed that co-culture of MDSCs with metastatic tumor cells, or exposure of MDSCs to tumor cell-conditioned medium, sustained the expression of CD79a in MDSCs in culture, and induced many of the same responses as did activation of CD79a by the anti-CD79a antibody." (PMID 24146823, 2013). "With our discovery of a functional role for CD79a in the tumor suppressive effects of MDSCs, it will be interesting to determine whether targeting CD79a or downstream signaling events would add to this arsenal of anti-MDSC approaches." (PMID 24146823, 2013). "Tumor-induced CD79a expression on MDSCs was also observed in human cancer patients, suggesting that CD79a on MDSCs may be a novel target for cancer therapy." (PMID 24146823, 2013). "The contribution of CD79a to the tumor-promoting effect of myeloid cells was assessed in two ways." (PMID 24146823, 2013). "CD79a on MDSCs is upregulated and activated in response to soluble factors secreted by tumor cells." (PMID 24146823, 2013). "Tumor cells appeared as mature large B cells with surface expression of CD79a and NK1.1 in FACS." (PMID 20046882, 2009). "Microscopically, a neoplasm infiltrates the colon wall and perivisceral adipose tissue; the neoplasm is formed by cells with morphology and immunophenotype of a mature plasma cell (CD79a+, CD138+, MUM1+, CD20-, and Bcl1-) with monotypic expression of K light chains and IgA heavy chains." (PMID 39267849, 2024). "Other studies also reported that CD79A and CD79B mutations modify distal BCR signaling in collaboration with other mutations of the BCR signaling network via modulation of NF-κB signaling (with an effect on survival, apoptosis, and proliferation of tumor cells)." (PMID 38203179, 2023). "Two cases (the paediatric case and one adult case) showed partial staining for CD20 but diffuse positivity for CD79a, with the paediatric case expressing MUM1 in 40% of tumour cells." (PMID 41047873, 2025). "The canonical markers EPCAM and KRT19 identified tumor cells, while CD3D, CD2, PTPRC, CD14, AIF1, CD79A, and COL1A2 validated non-tumor cells." (PMID 39955556, 2025). "The tumor showed strong expression of CD20, CD79a, PAX5, and Ki-67 (close to 90%), but CD3, CD56, and TIA1 were all negative." (PMID 41291370, 2025). "While lymphoid aggregates alone did not distinguish between responsive and non-responsive tumours, the integrated analysis revealed higher expression of genes like CD37, MS4A1, BLK, CD79A/B, and TNFRSF13C in responsive tumours’ lymphoid aggregates." (PMID 40141092, 2025). "B-ALL is a neoplasm of precursor lymphoid cells committed to the B-cell lineage, characterized by the expression of CD19, CD22, cytoplasmic CD79a, and/or PAX5, as determined by flow cytometry or immunohistochemistry." (PMID 41333696, 2025).
tumor (continued). "Tumor cells universally expressed CD20, with frequent positivity for CD19 (95.7%), CD79a (100%), MUM1 (83.8%), and BCL2 (92.1%), while CD10 (17.5%) and CD30 (10%) were less common." (PMID 41487580, 2025). "Immunohistochemistry confirmed the diagnosis, with tumor cells positive for CD20, CD79a, Bcl-6, and c-Myc, and a high Ki-67 proliferative index (>90%)." (PMID 40589634, 2025). "Diagnosis is primarily cytological, hinging on the classic “starry sky” appearance, alongside immunophenotyping that shows tumor cells positive for B‐cell markers (CD19, CD20, CD22, CD79a, CD38, PAX5) and germinal‐center markers (CD10, BCL6)." (PMID 40951226, 2025). "Immunohistochemical (IHC) studies of the bone trabeculae showed the intact structure, and the tumor cells exhibited strong diffuse positivity for CD20, CD79a, Pax-5, CD10, and BCL-2." (PMID 40746899, 2025). "The results showed that the methylation levels of FAM83E, CD79A, and SPINK7 were reduced in tumor tissues with poor clinical staging, while DKK1 was elevated in tumor tissues." (PMID 38518012, 2024). "In our study, we detected 1,993 cells with CD79A and CD79B expressions, consisting of 1,305 cells from the control samples and 688 cells from the tumor samples." (PMID 38386050, 2024). "Our findings indicated that CD79A, COL5A1, ERO1A, and GJB2 were significantly overexpressed in tumor tissues compared to normal tissues, while CD101 and CPA3 showed more active expression in normal lung tissues, aligning with our prior analysis." (PMID 39850883, 2024). "The majority of tumor cells that CD20 and CD79a are positive were found in the medullary area, leading to the destruction of the medullary cord structure in the medullary sinus." (PMID 39834941, 2024). "In contrast, tumor cells in DLBCL express common B cell antigens (CD20, CD79a, CD19), while CD30 is expressed in only 25% of cases." (PMID 39195213, 2024). "Lymphocyte related genes (CD3, CD8), B cell receptor related genes (CD40, CD79a), major histocompatibility complex (MHC) related genes (H2-Ab1, Ciita) were significantly downregulated in the tumor tissues of BDL mice." (PMID 38951890, 2024). "Based on above evidences, we had a strong desire to investigate the effects of the BCSC population with CD79A+ and CD24- on tumor immune microenvironment." (PMID 38066053, 2023). "According to the WHO definition, CLL/SLL cells typically co-express CD5 and CD23, and flow cytometry reveals that tumor cells express dim surface IgM/IgD, CD20, CD22, CD5, CD19, CD79a, CD23, CD43, and CD11c (weak)." (PMID 38258066, 2023). "Histologically, tumor cells conform to mature B cells (late germinal center exit), and thus they express typical mature B cell markers such as CD20, CD19, PAX5, or CD79a." (PMID 37872367, 2023). "Three representative markers, CD20, CD79A and CD79B, were used to test the accuracy of the tumor cell population." (PMID 37120690, 2023). "Other cell type‐specific markers were similarly detected in the primary tumours (CDH2, CD3D and CD79A), including a notably low detection of CD19 in B cell populations." (PMID 37691350, 2023). "mmunohistochemical staining showed that the tumor cells were positive for CD20, CD79a, PAX-5, Bcl6, MUM-1, CD19, c-Myc (Y69) (40%), and Bcl2 (80%)." (PMID 37884941, 2023). "Our data indicated that the “cold” tumor types like MB and EPN also contained the major classical immune cells, such as T cells (PTPRC, CD3D), B cells (CD79A, IGHG1, MZB1), and NK cells (KLRB1)." (PMID 38094301, 2023). "IHC analysis of patients showed that b-lymphocyte membrane markers (CD20 and CD79a), Bcl-2, Bcl-6 and MUM-1 were all positive in tumor cells." (PMID 36701728, 2023). "By evaluating VDJ regions across all three samples we observed >99% of all B cells (CD79A+) sequenced contained identical VDJ sequences, confirming the RT-phase tumor in this patient derived as a clonal progression from the existing CLL." (PMID 36609611, 2023).